MIR4760 (microRNA 4760)
Synonyms: hsa-mir-4760
Gene: MicroRNA gene on chromosome 21 (40,212,352 to 40,212,431, reverse strand). Ensembl gene ENSG00000263973.
Homologues: Orthologues: chimpanzee MIR4760 (100% identical).